IL10 (interleukin 10)
Diseases named in the same sentence as IL10 in open-access papers (continued):
Sharing a sentence is not in itself a finding about the gene and the disease.
lymphoma (continued). "Fifteen of the 31 lymphoma patients (48%) exhibited increased IL-10 and 5 patients (16%) exhibited increased IL-4 levels." (PMID 25541655, 2014). "Levels of IL-10 in the vitreous have been shown to be elevated in patients with intraocular lymphoma and significantly higher in eyes with lymphoma compared to uveitis." (PMID 23750271, 2013). "When a diagnosis of lymphoma is established, serial measurements of IL-10 is promising as a quantitative tool for monitoring disease status and therapeutic efficacy." (PMID 23750271, 2013). "Our findings demonstrate that aqueous levels of IL-10 and IL-10/IL-6 are elevated in lymphoma compared to uveitis." (PMID 23750271, 2013). "Compared to lymphoma or solid tumors (n = 20), acute leukemia subjects (n = 15) displayed significantly higher concentrations (P<0.05) of IL-6, IL-8, IL-10, and TNF-α and lower levels of pro-LL-37 (P<0.001)." (PMID 23741421, 2013). "Prior studies, have demonstrated elevated IL-10 levels in patients with lymphoma as well as elevated IL-10/IL-6 levels in lymphoma compared to uveitis." (PMID 23750271, 2013). "In our analysis, we selected the highest IL-10 and lowest IL-6 values in each patient with lymphoma and the lowest IL-10 and highest IL-6 values in each patient with uveitis." (PMID 23750271, 2013). "In a rank-sum test, IL-10 values were significantly higher in eyes with lymphoma than uveitis (U = 7.0; two-tailed p = 0.004)." (PMID 23750271, 2013). "Lastly, once lymphoma is diagnosed, IL-10 levels can be monitored over time to assess disease activity and therapeutic response." (PMID 23750271, 2013). "For example, overexpression has been found in lymphoma, whereas IL-10 deficiency was found in IBD, indicating that the dysregulation of IL-10 has a pathophysiological significance." (PMID 24046362, 2013). "Since CD40L and IL-10 are present in the lymphoma microenvironment, these proteins can contribute to BMP resistance." (PMID 23049692, 2012). "It has also been proposed that the IL-10 level alone can also be used as a surrogate marker of lymphoma and can be obtained from an anterior chamber paracentesis with reportedly good sensitivity and specificity." (PMID 23150722, 2012). "In EBV-positive HL, the lymphoma microenvironment is T-reg cell rich and the transformed cells secrete immunosuppressive cytokines and chemokines like IL10, CCL5, CCL20, and CXCL10." (PMID 22979947, 2012). "Patients with lymphoma are found to have low levels of proinflammatory IL-6, but higher levels of the anti-inflammatory cytokine IL-10 are produced by B cells." (PMID 23150722, 2012). "These PD-L1+ B cells predominantly exhibit a regulatory B-cell (Breg) phenotype, capable of secreting IL-10 and interacting with T cells through the PD-1/PD-L1 axis to suppress their immune function, thereby providing a favorable microenvironment for lymphoma immune escape." (PMID 40723865, 2025). "The highest AUC, with a good predictive value, was found for IL-10 > 39.87 pg/ml in separating EBER-positive lymphoma-associated hemophagocytic lymphohistiocytosis from non-neoplastic EBV-associated hemophagocytic lymphohistiocytosis." (PMID 40045277, 2025). "Interleukin-10 (IL-10), an anti-inflammatory cytokine produced by monocytes, macrophages, and tumor cells, contributes to the regulation of the blood–brain barrier and promotes lymphoma progression, thereby facilitating CNS infiltration." (PMID 40881684, 2025). "HDAC11 may also regulate IL-10 levels and MDSC expansion, while HDAC6 could influence IL-10 expression as a transcription factor, although this remains unproven in lymphomas." (PMID 40299416, 2025). "The IL-10 inhibitory peptide exerted an anticancer effect on lymphoma B cells and was able to eliminate the inhibitory effect of 1L-10 on macrophages; the computer-designed NK20a has improved IL-10 receptor binding affinity and can serve as a tool for developing anticancer strategies." (PMID 41300695, 2025).
lymphoma (continued). "IL-10, which is increased in the serum of patients with B-cell NHL, including DLBCL, and is produced by lymphoma cells, was shown to decrease HLA-DR expression on monocytes, and IL-10-induced CD14+HLA-DRlow cells inhibited the activation and proliferation of T cells." (PMID 41219641, 2025). "In addition, IL-10 signaling has been shown to promote lymphoma growth in vivo and tumor-derived IL-10 promotes immune escape in DLBCL." (PMID 39324141, 2024). "Moreover, the blockade of CCR1 inhibited protumor M2-like macrophage phenotype by decreasing CD206 and IL-10 expression and triggered a favorable anti-lymphoma activity." (PMID 39351239, 2024). "Human lymphoma patients with higher IL-10 producing MDSCs (but not Arg1 or iNOS) are associated with reduced anti-tumoural NK cells in blood." (PMID 38464388, 2024). "Lymphoma cells infiltrate and proliferate under the retina producing elevated levels of IL-10." (PMID 36674579, 2023). "However, the authors have found an increase in the serum concentration of IL-10 in dogs with lymphoma, which was the highest in B-cell type." (PMID 36009726, 2022). "Thus, we studied the expression of TNF-α and IL-10 as Th1 and Th2 mediated cytokines, respectively, involved in lymphoma patients in Iraq, especially given the high incidence of blood disease in this country." (PMID 35928372, 2022). "In addition, 15 patients were tested for IL-6 and IL-10 levels to assess inflammatory status and diagnose lymphoma." (PMID 35439966, 2022). "Previously, studies have argued for the likelihood of lymphomas secreting cytokines such as IL10 to prevent their recognition by the immune system, especially considering that the cells have honed to the vitreous only because it is protected from the immune system." (PMID 35158867, 2022). "Selected cytokines may result pivotal in the orchestration of such pathogenic DLBCL microenvironment, where deprivation of IL-21 or addiction to IL-10 can support tumour survival and modulate PD-L1 levels in the lymphoma cells." (PMID 34572910, 2021). "Interleukin 10 is a growth factor for malignant B cells, explaining the high levels in lymphoma." (PMID 34439078, 2021). "Later studies showed that a similar IL-10/IL-6 ratio could be measured in the aqueous, which can be readily collected for serial measurements to follow lymphoma over time." (PMID 34439078, 2021). "Indeed, in vitro exposure of monocytes to IL-10-rich supernatants obtained from lymphoma cells induced downregulation of HLADR expression, resulting in the phenotype of M-MDSCs with immunosuppressive function over T-cell proliferation." (PMID 34441758, 2021). "Interleukin (IL)-10, a cytokine produced by malignant B cells, has been recognized as a valuable cytokine in lymphoma; it is related to B-cell antibody production and its intraocular levels reflect the rate of malignancy of the lymphoma." (PMID 33009434, 2020). "IL-10 is rapidly produced and released by Bregs stimulated with lymphoma-derived small EVs." (PMID 31137912, 2019). "We tested if the transcriptional levels of SOCS1 (the only regulator reported in the literature to be associated with inhibition of IL-10 signaling in a lymphoma cell line) and SOCS3 (as control; it does not inhibit IL-10R) were increased by IFN-β treatment." (PMID 30061883, 2018). "Furthermore, cytokine analysis of IL-10 and IL6 ratios greater than 1.0 are suggested diagnostic criteria for lymphoma." (PMID 29954352, 2018). "In addition, a recent study has shown that the lymphoma-promoting tolerogenic function of IL-10 produced by DCs was regulated by the C/EBPβ transcription factor." (PMID 30544623, 2018). "Therefore, we studied the expression of IL-10 in lymphoma cell lines after treatment with ricolinostat alone and in combination." (PMID 28315173, 2017). "To determine whether these results were restricted to B16/F10 tumors, we performed the same experiment in WT and IL-10−/− mice using the E.G7-OVA lymphoma model." (PMID 27075020, 2016).
lymphoma (continued). "IL10 knockout experiments in mice have previously underlined its role in B1 cell expansion and development of CLL, whereas Mmp10 is potentially a novel CLL gene, which is known to be induced in lymphoma cells thereby accelerating the tumor growth." (PMID 27533467, 2016). "In this study a comprehensive analysis of the systemic levels of interleukins (IL-1,IL-6, IL-8,IL-10 and IL-12) was performed in 75 patients with different gastric neoplasms (cancer, gastrointestinal stromal tumors, neuroendocrine neoplasms, lymphomas) and 40 healthy volunteers." (PMID 26486258, 2015). "When the A20 cells were co-cultured with the MSCs for 48 h, the fraction of cells in which intracellular IL-10 could be detected increased from 1.74±0.59% to 4.64±0.89%, suggesting that MSCs influence the capacity of lymphoma cells to release IL-10." (PMID 25901937, 2015). "Similarly, endogenous IL-10 secreted by lymphoma cells also downregulates HLA-DR expression on CD14+ monocytes." (PMID 26230952, 2015). "Similarly, IL-10/IL-6 levels were significantly elevated in eyes with lymphoma (U = 6.0; two-tailed p = 0.003)." (PMID 23750271, 2013). "Statistical indices for threshold values of IL-10/IL-6 for discriminating lymphoma from uveitis." (PMID 23750271, 2013). "Additionally, in our study, both IL-10 and IL-10/IL-6 cytokine markers were moderately accurate tools for discriminating lymphoma from uveitis." (PMID 23750271, 2013). "Compared to eyes with uveitis, eyes with lymphoma had higher levels of IL-10 (U = 7.0; two-tailed p = 0.004) and IL-10/IL-6 (U = 6.0; two-tailed p = 0.003), whereas IL-6 levels were more elevated, although insignificant, in those patients with uveitis than in lymphoma (U = 15.0; two-tailed p = ns)." (PMID 23750271, 2013). "Here, we evaluate the utility of IL-10, IL-6 and IL-10/IL-6 for discriminating lymphoma from uveitis and report the effects of intraocular methotrexate and rituximab on aqueous cytokine levels in eyes with lymphoma." (PMID 23750271, 2013). "Selecting the highest IL-10 and lowest IL-6 level for each patient with lymphoma and the lowest IL-10 and highest IL-6 level for each patient with uveitis yielded a total of 10 data points from 10 patients with lymphoma and 7 data points from 7 patients with uveitis." (PMID 23750271, 2013). "Statistical indices for threshold values of IL-10 for discriminating lymphoma from uveitis." (PMID 23750271, 2013). "Furthermore, CD5+ B lymphoma cells produce increased levels of IL-10 relative to CD5− lymphoma cells." (PMID 20625435, 2010). "IL-10 and TNFα are well-known growth factors for lymphoma and myeloma cell lines." (PMID 19956602, 2009). "In gastric, colon, lymphomas and renal cell cancer, increased IL-10 production has been associated with a negative prognosis." (PMID 19040745, 2008). "Therefore, it can be hypothesized that an increase in IL-10 serum concentration contributes to the reduction of MHCII expression on monocytes in dogs with lymphoma." (PMID 36009726, 2022). "Interestingly, driven by the increased IL-10 serum levels in lymphoma patients, they sought to address whether IL-10 may trigger M-MDSC development." (PMID 34441758, 2021). "IL-10 is produced by the lymphoma cells and could have both autocrine and paracrine effects." (PMID 34680209, 2021). "Moreover, an immunosuppressive tumor microenvironment, with tons of interleukin 6 (IL-6), IL-10, EBV-encoded microRNAs, and C-C motif chemokine receptor 4 (CCR-4)+ regulatory T-cells (Treg), may aid lymphoma cell survival in immunocompetent individuals." (PMID 33564306, 2021). "Thus, overexpression of IL-10 by PTCL lymphoma cells may damage the host’s immune system, resulting in immunosuppression and tumor escape." (PMID 33154947, 2020). "However, one could also make a different comment: if an increasing IL-10 level is accompanying NHL, the increased IL-10 may be a reaction of the immune system, and supporting this reaction may help to control the aggression of lymphoma." (PMID 25541655, 2014).
lymphoma (continued). "However, elevated IL-10 and IL-10/IL-6 values are indicative of lymphoma." (PMID 23750271, 2013). "The lymphomas secreted Il-10, which might help in the promotion of metastasis and lymphoma growth." (PMID 21269511, 2011). "Stromal cells, including follicular dendritic cells and macrophages, secrete cytokines and chemokines such as IL-10, TNF-α, and CXCL12, which enhance lymphoma cell survival and proliferation." (PMID 41180747, 2025). "Previous study showed high levels of IL-10, IL-6, IL-1β, and TNF-α in lymphoma patients except TNF-α in NHL patients." (PMID 40076681, 2025). "Plasma exosomes from EBV-infected lymphoma cells, which mainly contain BART-miRNAs, function similarly to pro-inflammatory cytokine to trigger the secretion of ARG1, TNF-α, and IL-10 in monocytes and macrophages." (PMID 36411555, 2024). "In a mouse model of lymphoma, tumor growth was substantially reduced and memory CD8+ T-lymphocytes were increased in mice that were injected with IL-10 immediately following a booster vaccine relative to mice that were not inoculated and received no IL-10." (PMID 38928185, 2024). "This increase in IL-10 was probably due to the presence of EBV in those lymphoma cells, since it is known that EBV infection can increase IL-10 production in B cells and that this has been related to cell death inhibition and, therefore, to tumor growth." (PMID 36680271, 2023). "And the STAT3 (rs744166), IL2 (rs2069762), IL10 (rs1800871), and PARP1 (rs907187) manifested a significant relationship with the peripheral blood counts in lymphoma patients." (PMID 37329186, 2023). "For lymphoma patients with NHL and HL, TNF-α and IL-10 levels were higher than normal levels before RSV treatment." (PMID 35928372, 2022). "At diagnosis, IL10, IL6 and BAFF cytokine serum levels were higher in cHL patients with advanced-stage (Ann Arbor III-IV) lymphoma compared to patients with localized disease (p = 0.002, p = 0.03 and p = 0.01, respectively)." (PMID 35008292, 2021). "The decreased IL-12/IL-10 ratio in DCs from untreated tumor-bearing mice is likely a consequence of IFN-γ suppression, which occurs in the microenvironment of growing λ-MYC lymphomas." (PMID 33141285, 2021). "What is more, serum IL-10 concentration is also an important prognostic factor for various tumors, such as diffuse large B-cell lymphoma (DLBCL) and adult T-cell leukemia/lymphoma (ATL)." (PMID 33154947, 2020). "The inhibition of LPS-induced TNF-α expression in macrophages has been shown to be mediated by IL-10, the expression of which is promoted by BCL3 (B-Cell Leukemia/Lymphoma)." (PMID 32759853, 2020). "Further investigation of a KoRV-B- and C-positive adult koala that died (found to have lymphoma) revealed immunosuppression characterized by a decreased CD4:CD8b ratio and increased IL-10 expression." (PMID 33316950, 2020). "Our result showed high levels of IL-10, IL-6, IL-1β, and TNF-α in lymphoma patients compared with control." (PMID 30814315, 2019). "Blockade of CD47 using TTI-621 significantly increased phagocytosis of lymphoma cells by all macrophage subsets, with M(IFN-γ), M(IFN-γ+LPS) and M(IL-10 + TGFβ) macrophages having the highest phagocytic response." (PMID 29084248, 2017). "The concentration of IL-10 in CSF from PCNSL and SCNSL patients was also markedly elevated compared with non-lymphoma comparators (p < 2.3 × 10−5)." (PMID 24969265, 2014). "Expression of B cell-stimulatory cytokines IL-1β, IL-6, IL-10, IL-12p40, IL-13 and TNFα and HIV proteins p17, gp120 and nef were elevated in the Tg mice with lymphoma." (PMID 23985023, 2013).
lymphoma (continued). "We have, herein, described two cases of lymphoma in which treatment with intraocular MTX and RTX was shown to decrease IL-10 concentrations to undetectable levels over time." (PMID 23750271, 2013). "Recently, EBERs were found to increase transcription or mRNA stability of IL-10, IL-9, or IGF1 in lymphoma or carcinoma cell lines." (PMID 20144199, 2010). "Our data suggested that CD8+ Tfr cells might engage with lymphoma B cells and DCs via ICOS/ICOSL interactions, potentially stabilising FOXP3 function but also increasing IL‐10 production by Tregs, enhancing suppressive potency." (PMID 41190308, 2025). "Administration of IL-10 to lymphoma-bearing mice significantly curtailed tumor growth, with a noteworthy rise in memory CD8 + T cells in comparison to non-IL-10-injected mice, suggesting IL-10’s to enhance anti-tumor effects, immunity, and conceivably play a role in cancer recurrence prevention." (PMID 38671015, 2024). "IL-10 was detected at the nonlymphoma ATA B cell stage, and the lymphoma stage showed strongly increased IL-10 expression and CD1b/Mac1+IL-6+IL-10++ in ATA B lymphoma." (PMID 36050343, 2022). "We found that compared with healthy people and uninfected lymphoma patients, IL-6 and IL-10 were significantly increased in G- bacterial infections, while IL-6 was significantly increased and IL-10 was not significantly increased in G+ bacterial infections." (PMID 35432366, 2022). "These IL-21-impaired TFH cells in DLBCL may also promote a cytokine switch towards IL-10 production by TFR cells, further contributing to lymphoma maintenance and progression." (PMID 34572910, 2021). "Therefore, the authors concluded that MDSC suppressive activity was mediated by the release of IL-10 and S100A12 and the increased expression of programmed death-ligand 1 (PD-L1) by lymphoma cells." (PMID 34441758, 2021). "The role of MDSC in IL-10 production is suggested by results in B-cell NHL patients and lymphoma murine models, but serum IL-10 could also be produced by lymphoma cells and contribute to an increased number of M-MDSC." (PMID 33603754, 2020). "Human lymphoma cells may produce many inhibitory factors such as PGE2, VEGF, IL-10 and TGF-beta that can suppress T cell function, and several of these factors may be involved in the induction of Treg cells." (PMID 29267390, 2017). "Physicians should be familiar with the clinical phenotype of IL-10 signaling defects in order to enable prompt diagnosis at an early age and referral for allogeneic HSCT, before later complication occur, such as development of lymphoma." (PMID 26822028, 2016). "While negative IL-10 and IL-10/IL-6 values do not exclude a diagnosis of lymphoma, elevated levels do appear to be consistent with lymphoma clinically." (PMID 23750271, 2013). "A plausible reason is that reactive T cells are also an important part of the vitreous cells in eyes with VRL; if the proportion of lymphoma cells is low, IL-10 may not correlate well with the extent of vitreous haze." (PMID 40468390, 2025). "Regarding possible triggers, lymphoma-complicated CLS patients have elevated levels of various cytokines, such as granulocyte colony-stimulating factor (G-CSF), interleukin-6 (IL-6), interleukin-10 (IL-10), interferon-gamma (IFN-γ) and tumor necrosis factor alpha (TNF-α)." (PMID 39072323, 2024). "In this experiment, IL-10 cytokine incubation alone did not significantly promote the proliferation of lymphoma B cells, as the B cells themselves could produce endogenous IL-10." (PMID 38102207, 2023). "Our findings, which are supported by two independent lymphoma patient datasets, propose PDGFRβ is yet another potent kinase in the list of regulators of IL-10 expression in ALCL and that targeting the PDGFRβ/STAT5/IL-10 axis is an attractive therapeutic strategy." (PMID 36045346, 2022).